PRDX6 (peroxiredoxin 6)
Diseases named in the same sentence as PRDX6 in open-access papers (continued):
Sharing a sentence is not in itself a finding about the gene and the disease.
Stroke (9 papers, 2017 to 2025). Sudden impairment of blood flow to a part of the brain due to occlusion or rupture of an artery to the brain. "Additionally, Park7, Prdx6, and Jun in plasma EVs might serve as markers of pathological processes associated with stroke." (PMID 41164797, 2025). "PRDX2 and PRDX6 have been shown to have a positive effect on brain tissue after stroke by reducing the level of ROS and thus its harmful effects and mitigating neuronal apoptosis in rats and dogs." (PMID 40332314, 2025). "In this study, four biomarkers, CDKN1A, GPX4, PRDX1, and PRDX6, were used to diagnose stroke and assess the treatment effects." (PMID 38360841, 2024). "Prdx6 upregulation by Cur treatment attenuates ischemic oxidative damage through SP1 induction in rats after stroke." (PMID 28596967, 2017). "However, Prdx6 was proven to be released from necrotic brain cells within 12 h after stroke onset, coinciding with the timing of leukocyte infiltration, then initiating destructive immune responses acting as an endogenous ligand for TLR2 and TLR4." (PMID 38671897, 2024). "A sustained upregulation of Prdx6 expression may protect hippocampal neurons from oxidative stress in a rat model of stroke (localized heat-induced brain injury in the left anterior cortical tectum)." (PMID 38671897, 2024). "Curcumin treatment upregulated the expression of Prdx6 to attenuate neurological deficits and oxidative stress in cerebral ischemia/reperfusion (I/R) rats, suggesting that Prdx6 has a neuroprotective effect against oxidative stress in rats after stroke." (PMID 38671897, 2024). "Our hypothesis is that Cur exerts neuroprotective effects through activation of Prdx6/SP1 during a stroke." (PMID 28596967, 2017). "Inhibition of Prdx6-iPLA2 activity by gene therapy and/or pharmacology may constitute a promising new therapeutic approach to the treatment of stroke." (PMID 28424593, 2017). "Inhibition of Prdx6 iPLA2 activity by gene therapy and/or pharmacological means may constitute a promising new therapeutic approach to the treatment of stroke." (PMID 28424593, 2017). "Therefore, this interesting phenomenon led us to speculate that PRDX6, with its specific function and structure, may be a key molecule involved in the controversial role of astrocytes in stroke." (PMID 38287382, 2024). "However, Prdx6 is also involved in the proinflammatory signals after stroke." (PMID 36671018, 2023). "However, the role of the independent phospholipase A2 (iPLA2) activity of Prdx6 in stroke has not been well studied." (PMID 28424593, 2017).
bladder cancer (8 papers, 2007 to 2026). "It demonstrated that enhanced PRDX6 expression was strongly associated with bladder cancer development." (PMID 38544826, 2024). "Our research indicates that PRDX6 can promote the progress of bladder cancer and is associated with poor prognosis, while the specific mechanism of action needs further study." (PMID 36741702, 2022). "Quan and colleagues demonstrated that enhanced PRDX6 expression was strongly associated with bladder cancer development." (PMID 17980029, 2007). "In bladder cancer, PRDX6 promoted the proliferation and cell cycle of bladder cancer cells through JAK2/STAT3 signalling pathway." (PMID 38506082, 2024). "T24 and TCCSUP bladder cancer cell lines were used for PRDX6 knockdown and analysis of cell growth and cell cycle." (PMID 34246267, 2021). "To date, PRDX6 is relatively insufficient in the study of bladder cancer." (PMID 36741702, 2022). "The bone marrow mesenchymal stem cell (BMSC)-derived lncRNA Mir9-3hg, which has been previously reported to suppress bladder cancer progression, can suppress I/R-induced cardiomyocyte ferroptosis by regulating the pumilio RNA binding family member 2 (Pum2)/peroxiredoxin 6 (PRDX6) axis." (PMID 36358568, 2022). "Weighted gene co-expression network analysis (WGCNA), protein–protein interaction (PPI) network mutual analysis, and the Kaplan–Meier survival prognosis analysis were used to identify six key genes associated with the prognosis of bladder cancer: VEGFA, ANXA1, HSP90B1, PSMA7, PRDX6, and PPP1CB." (PMID 36741702, 2022). "The Kaplan–Meier survival prognosis analysis was performed on the top 100 genes, and 6 genes related to the survival prognosis of bladder cancer were finally screened out: VEGFA, ANXA1, HSP90B1, PSMA7, PRDX6, and PPP1CB." (PMID 36741702, 2022). "According to BC values and the Kaplan–Meier survival curve, six genes related to the occurrence and development of bladder cancer were screened out: VEGFA, ANXA1, HSP90B1, PSMA7, PRDX6, and PPP1CB." (PMID 36741702, 2022).
colon carcinoma (8 papers, 2009 to 2024). "Of these, Mpp1 is associated with the cytoskeleton and cell proliferation, Prdx6 is associated with migration and invasion in colon cancer, and Epb4.2 predicts survival outcomes in pancreatic cancer." (PMID 38542101, 2024). "PRDX1 overexpression and PRDX6 under-expression were also shown in the stem-like colonospheres from colon cancer cells." (PMID 32231717, 2020). "Dy-regulations of the PRDX1 and PRDX6 were also confirmed in the stem-like colonospheres from colon cancer cells." (PMID 32231717, 2020). "Induction of ferroptosis has been considered an effective strategy for tumor therapy, hence, PRDX6 silencing might be a good therapeutic option to enhance ferroptosis and diminish the viability of colon cancer cells." (PMID 39061949, 2024). "Conversely, the protein expression of PRDX5 and PRDX6 was lower in colon cancer tissues." (PMID 36969053, 2023). "Our research suggested that GSTP1 and PRDX6 might take part in the MDR of human colon carcinoma." (PMID 35509845, 2022). "Here, down-regulation of PRDX6 in COAD was confirmed both at mRNA and protein level and its under-expression in the colonospheres form primary colon cancer cells were shown." (PMID 32231717, 2020). "Third, to evaluate the methylation status of PRDX6 an NDRG2 genes in normal and cancer tissues, as well as in colon cancer cell lines, bisulphite sequencing analysis was used." (PMID 19257893, 2009). "In summary, the absence of PRDX6 in colon cancer cells increases ROS and oxidative damage in the form of lipid peroxides." (PMID 39061949, 2024).
cervical carcinoma (7 papers, 2016 to 2025). A carcinoma arising from either the exocervical squamous epithelium or the endocervical glandular epithelium. "However, to inhibit the occurrence and development of cervical cancer, the molecular mechanism underlying the function of PRDX6 in cervical carcinogenesis or progression needs further exploration." (PMID 32201510, 2020). "PRDX6 is notably overexpressed in cervical cancer tissues, where its overexpression promotes proliferation, migration, and invasion of cancer cells while inhibiting apoptosis." (PMID 39640883, 2024). "In another study, overexpression of PRDX6 promoted pathological tumorigenesis conditions in cervical cancer cells." (PMID 37501157, 2023). "In conclusion, our study illustrated that PRDX6 serves as a tumor promoter gene and results in the stimulation of proliferation, migration and invasion, as well as the suppression of apoptosis, in cervical cancer cells." (PMID 32201510, 2020). "The results were consistent with the effects of PRDX6 on cultured cervical cancer cells in vitro, which demonstrated the activity of promoting cancer progression of PRDX6 in vitro and in vivo." (PMID 32201510, 2020). "In the present study, we regulated the expression level of PRDX6 in SiHa cells to evaluate the proliferation, apoptosis, migration and invasion capacities of cervical cancer cells." (PMID 32201510, 2020). "The results indicated that PRDX6 was significantly overexpressed in cervical cancer compared to normal cervical tissues." (PMID 32201510, 2020). "The PRDX6 protein was mainly localized in the cytoplasm of cervical cancer cells and PRDX6 expression was remarkably increased in cancerous tissues compared with normal cervical tissues (7.8 ± 3.4 vs. 2.4 ± 2.4, P < 0.01)." (PMID 32201510, 2020). "However, the potential mechanism, including related signal transduction pathways, involved in the functions of PRDX6 on the proliferation and differentiation of cervical cancer cells needs to be further explored." (PMID 32201510, 2020). "In the present study, we investigated the expression level of PRDX6 in cervical cancer tissues." (PMID 32201510, 2020). "The PRDX6 expression level in different cervical cancer cells was analyzed by western blot method." (PMID 32201510, 2020). "In addition, the overexpression of PRDX6 significantly promoted the growth of cervical carcinoma in vivo." (PMID 32201510, 2020). "Therefore, the present study aimed to investigate the expression of PRDX6 in cervical cancer compared with normal cervical tissues, and explore its effect on the biological behavior of cervical cancer cells." (PMID 32201510, 2020). "We further explored whether PRDX6 was involved in the tumorigenesis of cervical cancer in vivo, in which a SiHa cell xenograft tumor model was used in the BALB/c nude mice." (PMID 32201510, 2020). "Additionally, the effect of PRDX6 on the progression of the cervical cancer was investigated via a xenograft model in BALB/c nude mice that either overexpressed or underexpressed PRDX6." (PMID 32201510, 2020). "Conversely, PRDX6 knockdown significantly inhibited tumor growth (P < 0.01), decreased PCNA protein expression, and enhanced green TUNEL fluorescence, which demonstrated that downregulation of PRDX6 suppressed the proliferation, and promoted the apoptosis of cervical cancer in vivo." (PMID 32201510, 2020). "However, there was little information about the effect of PRDX6 in the human cervical cancer." (PMID 32201510, 2020). "However, the functional role of PRDX6 in the progression of cervical cancer is still unclear." (PMID 32201510, 2020). "In addition, PRDX6 protein level in SiHa cell line is moderate among these five cervical cancer cell lines, in which the PRDX6 expression was relatedly easy to be upregulated or downregulated to further explore the biological effect of PRDX6 in human cervical cancer." (PMID 32201510, 2020).
cervical carcinoma (continued). "Peroxiredoxin 6 (PRDX6), an antioxidant enzyme involved in the ROS pathway, is overexpressed in various cancers, such as cervical cancer, CRC, as well as in MDA-MB-231 HM BC cell line." (PMID 37834160, 2023). "In our previous study, we found that the expression level of PRDX6 was significantly downregulated in cervical cancer tissues after neoadjuvant chemotherapy through proteomic technology, indicating that it may play an important role in chemotherapy of cervical cancer patients." (PMID 32201510, 2020). "However, the role of PRDX6 in cervical cancer progression and metastasis has not yet been reported." (PMID 32201510, 2020).
diabetes (7 papers, 2013 to 2022). "While upregulation of Prdx6 is protective, it is also associated with several pathologies ranging from aortic lesions to diabetes susceptibility." (PMID 30871234, 2019). "Reports elsewhere indicate that the pathophysiological impairments associated with diabetes, such as sarcopenia (loss of muscle mass), muscle atrophy, and diabetic myopathy can potentially be rescued by Prdx6." (PMID 30871234, 2019). "Moreover, associations between Prdx6 expression and inflammatory endothelial phenotype are possible factors in endothelial dysfunction with diabetes." (PMID 30871234, 2019). "Previously, we demonstrated that knockout mice for peroxiredoxin 6 (Prdx6-/-), an antioxidant enzyme with both peroxidase and phospholipase A2 activity, develop a mild form of diabetes mellitus with a reduction in GSIS and in peripheral insulin sensitivity." (PMID 35370943, 2022). "We moved forward by showing higher levels of SA-β-Gal activity in skeletal muscle of Prdx6-/- mice that are prone to develop diabetes." (PMID 32316601, 2020). "The data demonstrated the expected destruction of pancreatic β cells in advanced diabetes and indicated that PRDX6 markedly increased the β cell mass, thus supporting a protective function of the antioxidant enzyme." (PMID 32908936, 2020). "Thus, Prdx6 could potentially represent diabetes susceptibility in humans." (PMID 30871234, 2019). "Of note, Prdx6 just recently has been identified as an important player in diabetes pathology as knockout of Prdx6 led to impaired insulin production and reduced muscular glucose up-take in mice." (PMID 26324419, 2016). "In conclusion, based on previous evidence and present results, Prdx6 may be considered a potential biomarker for diabetes mellitus and a novel therapeutic target for metabolic diseases." (PMID 35370943, 2022). "The link between diabetes, inflammation, and Prdx6 is not clear." (PMID 30871234, 2019).
esophageal cancer (7 papers, 2017 to 2024). A primary or metastatic malignant neoplasm involving the esophagus. "On the contrary, the down-regulation of PRDX6 could reduce the invasion ability of esophageal cancer cells." (PMID 38544826, 2024). "PRDX6 was up-regulated in various cancers such as breast, lung, and oesophageal cancer." (PMID 33053689, 2020). "We previously showed that autoantibody against PRDX6 could serve as a potential serum biomarker for early detection of NPC and esophageal cancer." (PMID 28184180, 2017).
ischemic stroke (7 papers, 2017 to 2025). A stroke disorder caused by obstruction of blood flow to the brain, due to thrombotic (local blood clot formation) or embolic (due to a blood clot or other material traveling from another site) event. "MJ33, PRDX6D140A mutation was used to block PRDX6-iPLA2 activity in vitro and vivo after ischemic stroke." (PMID 38287382, 2024). "This study aimed to explore whether PRDX6-iPLA2 regulates the function of astrocytes and astrocyte-induced microglial polarization in response to ischemic stroke and to identify the potential underlying mechanisms." (PMID 38287382, 2024). "Further research has shown that after ischemic stroke, PRDX6-iPLA2 produced by astrocytes can activate NADPH oxidase 2 (NOX2) pathway and microglia, thereby promoting the generation of ROS and driving inflammatory response." (PMID 41035004, 2025). "The findings indicate that after ischemic stroke, astrocytes can activate microglia and promote inflammatory responses through the production or secretion of factors such as PRDX6, sANPEP, Ca2+, and S100B." (PMID 41035004, 2025). "In ischemic stroke, PRDX6 is mainly expressed in astrocytes and PRDX6-iPLA2 is involved in the activation of astrocytes and microglia." (PMID 38287382, 2024). "To observe the changes in the four biomarkers CDKN1A, GPX4, PRDX1, and PRDX6 in patients with ischemic stroke, we measured their expression of these four biomarkers in peripheral blood using RT-PCR." (PMID 38360841, 2024). "Recently, studies had proved that PRDX6 was involved in cancer, inflammatory diseases, ischemic stroke, traumatic brain injury and neural degenerative diseases." (PMID 36120430, 2022). "Our study went further to demonstrate that expression of Prdx6 mRNA and protein is increased in the Cur + I/R group relative to I/R group, suggesting that Cur treatment upregulates the expression of Prdx6 after ischemic stroke." (PMID 28596967, 2017). "For instance, in the central nervous system, PRDX6-aiPLA2 has been reported to aggravate neuroinflammation following ischemic stroke by modulating astrocyte-induced M1 microglia activation and promoting the secretion of neurotoxic inflammatory mediators, including IL-1β, IL-17, and IL-23." (PMID 40298631, 2025). "PRDX6-iPLA2 inhibition reduced the levels of these pro-inflammatory cytokines and the number of CD16 + microglia, and increasing the number of CD206 + microglia after ischemic stroke." (PMID 38287382, 2024). "The results showed that CDKN1A, PRDX1, and PRDX6 expression levels were significantly increased, which was consistent with our study, suggesting that CDKN1A, PRDX1, and PRDX6 may be involved in the occurrence and development of ischemic stroke." (PMID 38360841, 2024). "However, there is a lack of reports on the role of aiPLA2 activity of Prdx6 in ischemic stroke." (PMID 34970121, 2021).
Parkinson disease (7 papers, 2017 to 2025). A progressive degenerative disorder of the central nervous system characterized by loss of dopamine producing neurons in the substantia nigra and the presence of Lewy bodies in the substantia nigra and locus coeruleus. "The hub genes connecting these processes included parkinsonism‐associated deglycase (Park7), peroxiredoxin 6 (Prdx6), Jun proto‐oncogene (Jun), and calreticulin." (PMID 41164797, 2025). "Peroxiredoxin 6 expression is also greatly increased in Parkinson’s disease substantia nigra, as is glutathione peroxidase 1 in cingulate gyrus and middle frontal gyrus (substantia nigra was not investigated)." (PMID 28820437, 2017). "In contrast, NQO1 and peroxiredoxin 6 are strongly expressed in astrocytes in substantia nigra of Parkinson’s disease brain, with more infrequent expression in neurons." (PMID 28820437, 2017).
prostate carcinoma (7 papers, 2009 to 2026). A carcinoma that arises from epithelial cells of the prostate gland. "Thus, overexpressed peroxiredoxin 6 in MCF-7 cancer cells (1.8-fold) and PC3 cancer cells (8.5-fold) indicates its role in breast and prostate cancer development." (PMID 38249992, 2024).